CES3 (carboxylesterase 3)
Description:
Involved in the detoxification of xenobiotics and in the activation of ester and amide prodrugs. Shows low catalytic efficiency for hydrolysis of CPT-11 (7-ethyl-10-[4-(1-piperidino)-1-piperidino]- carbonyloxycamptothecin), a prodrug for camptothecin used in cancer therapeutics.
Synonyms: FLJ21736; ES31
Tractability: Small molecule: it belongs to a druggable protein family. Antibody: UniProt predicts a signal peptide or a membrane-spanning region. PROTAC: its protein half-life has been measured.
Gene: Protein-coding gene on chromosome 16 (66,961,245 to 66,975,149, forward strand). Ensembl gene ENSG00000172828.
Subcellular location: Endoplasmic reticulum lumen
Subcellular location (Human Protein Atlas): Endoplasmic reticulum; Nuclear membrane
Pathways (Reactome):
Metabolism: Phase I - Functionalization of compounds
Transport of small molecules: LDL clearance
Gene Ontology:
Molecular function: protein binding; carboxylesterase activity; carboxylic ester hydrolase activity
Biological process: low-density lipoprotein particle clearance; xenobiotic metabolic process
Cellular component: extracellular exosome; cytosol; endoplasmic reticulum lumen
Genetic constraint (gnomAD): Loss-of-function variants: 50 observed, 64.15 expected, observed/expected ratio (o/e) 0.78, 90% interval 0.62 to 0.99. The upper end of that interval is the gene's LOEUF score, 0.99, which puts it in group 4 of 6, group 1 being the genes least tolerant of losing a copy. Missense variants: 645 observed, 779.76 expected, observed/expected ratio (o/e) 0.83, 90% interval 0.77 to 0.88. Synonymous variants: 266 observed, 295.19 expected, observed/expected ratio (o/e) 0.9, 90% interval 0.81 to 1.
Homologues: Orthologues: chimpanzee CES3 (98% identical), pig CES3 (74% identical), rabbit CES3 (73% identical), mouse Ces3b (66% identical), mouse Ces3a (65% identical), guinea pig CES3 (51% identical), tropical clawed frog ces2.3 (42% identical), zebrafish ces2b (38% identical), Drosophila melanogaster Jhe (28% identical), Caenorhabditis elegans ace-4 (27% identical), Drosophila melanogaster CG4757 (27% identical), Drosophila melanogaster Jhedup (27% identical), and 38 more. Paralogues in human: CES2 (45% identical), CES5A (43% identical), CES1 (42% identical), CES4A (40% identical), NLGN2 (34% identical), NLGN1 (34% identical), NLGN3 (33% identical), NLGN4X (32% identical), ACHE (32% identical), NLGN4Y (31% identical), TG (30% identical), BCHE (30% identical), and 1 more.
Diseases named in the same sentence as CES3 in open-access papers:
CES3 is named in the same sentence as 12 diseases in open-access papers, as found by Europe PMC text mining. Sharing a sentence is not in itself a finding about the gene and the disease. The quoted sentences say what the papers report.
Hepatic steatosis (2 papers, 2016 to 2025). Steatosis is a term used to denote lipid accumulation within hepatocytes. "In this study we found that mice lacking triacylglycerol hydrolase (TGH, also known as carboxylesterase 3 or carboxylesterase 1d) are protected from high-fat diet (HFD) - induced hepatic steatosis via decreased lipogenesis, increased fatty acid oxidation and improved hepatic insulin sensitivity." (PMID 27181051, 2016).
liver cancer (2 papers, 2023 to 2026). An epithelial or non-epithelial malignant neoplasm that arises from the liver. "Additionally, CES3 expression is reduced in early liver cancer, and its restoration is associated with decreased tumor development, suggesting a protective metabolic role in cancer." (PMID 41438579, 2026). "A preventive role of CES3 protein has been reported in the early stages of liver cancer development." (PMID 37215979, 2023).
Obesity (2 papers, 2014). Accumulation of substantial excess body fat. "Microarray data revealed also that a novel obesity-associated gene, Ces3, was down-regulated by metformin exposure in the neonatal adipose tissue." (PMID 25541979, 2014). "Ces3 codes for carboxylesterase 1D, which has recently been connected to obesity, diabetes and lipid metabolism." (PMID 25541979, 2014). "Taken together with the results of these previous studies, CES3 might be down-regulated in CP rats as a result of hyperglycemia or physiological adaptation to obesity." (PMID 24468282, 2014). "Further studies are needed to clarify the relationship between CES3 and PPAR signaling, but the results suggest that PPAR signaling could be important targets in obesity, obesity-induced inflammation, and metabolic syndrome." (PMID 24468282, 2014).
atherosclerosis (1 paper, 2017). A disease characterized by the build-up of fatty material and calcium deposition in the arterial wall resulting in partial or complete occlusion of the arterial lumen. "Similar to loss of hepatic Ces3/Ces1d function, inactivation of hepatic Ces1/Ces1g in Apoe−/− mice aggravated the development of atherosclerosis." (PMID 29259301, 2017).
cancer (2 papers, 2022 to 2026). A tumor composed of atypical neoplastic, often pleomorphic cells that invade other tissues. "Targeting lipid metabolic pathways, including enzymes like CES3, holds promise for cancer therapy but also presents inherent challenges and potential risks." (PMID 41438579, 2026). "Carboxylesterase 3 (CES3) encodes an enzyme that has a wide range of activities associated with the lipid-metabolism, has a possible preventive role in cancer." (PMID 35498757, 2022). "Inhibiting the function of CES3 might be a promising strategy in cancer treatment." (PMID 41438579, 2026).
tumor (2 papers, 2023 to 2026). "They found that higher CES3 expression is associated with better patient prognosis and improved immunotherapy efficacy, likely through its relationship with tumor-infiltrating immune cells." (PMID 41438579, 2026). "Studies have shown that deletion of CES3 reduces plasma triglyceride (TG), fatty acid, and cholesterol levels, improves insulin sensitivity, and reduces tumor weight in tumor-bearing mice." (PMID 41438579, 2026). "Collectively, these studies highlight CES3 as a potential biomarker and therapeutic target involved in modulating tumor metabolism, immune response, and progression across multiple malignancies." (PMID 41438579, 2026). "Their study also revealed that Angiotensin-Converting Enzyme 2 (ACE2), functioning within this metabolic network alongside CES3, suppresses tumor progression by regulating metabolic and oxidative stress pathways." (PMID 41438579, 2026). "One of the most striking examples from this analysis was CES3, which showed both reduced gene expression and reduced accessibilities of associated enhancer peak in BAP1-mutant tumor cells." (PMID 36973268, 2023). "We identified a potential CES3 enhancer peak located ~5 kb upstream of the CES3 transcriptional start site (TSS), displaying consistently lower accessibility in tumor cells of all BAP1 mutants as compared with other tumors and PT cells from NATs." (PMID 36973268, 2023). "Building on this evidence, our study investigates the role of CES3 in NSCLC, exploring how CES3-mediated lipid metabolic pathways may contribute to NSCLC progression and tumor biology." (PMID 41438579, 2026). "Application of these state-of-the-art tools to NSCLC models could further clarify the dynamic regulation of CES3 and TFAP2A in the tumor microenvironment and identify biomarkers predictive of response to metabolism-targeted therapies." (PMID 41438579, 2026).
CES3 also shares sentences with these, for which no sentence is quoted: colonic adenocarcinoma (1 paper); diabetes (1); hepatocellular carcinoma (1); Hyperglycemia (1); metabolic syndrome (1); schizophrenia (1).